LINC00404 (long independently transcribed non-coding RNA 404)
Gene: Long non-coding RNA gene on chromosome 13 (112,105,259 to 112,106,882, reverse strand). Ensembl gene ENSG00000229520.
Diseases named in the same sentence as LINC00404 in open-access papers:
LINC00404 is named in the same sentence as 4 diseases in open-access papers, as found by Europe PMC text mining. Sharing a sentence is not in itself a finding about the gene and the disease. The quoted sentences say what the papers report.
metastatic disease (1 paper, 2025). "Here, DNA hypermethylation of CpG sites within the LINC00404 gene in RCC is associated with advanced and metastatic disease, as well as with RCC metastases." (PMID 40647502, 2025).
LINC00404 also shares sentences with these, for which no sentence is quoted: cancer (1 paper); renal cell carcinoma (1); tumor (1).